CGAS (cyclic GMP-AMP synthase)
Diseases named in the same sentence as CGAS in open-access papers (continued):
Sharing a sentence is not in itself a finding about the gene and the disease.
brain disorder (1 paper, 2026). A disease affecting the brain or part of the brain. "We also summarize current pharmacological inhibitors targeting cGAS and STING and discuss their therapeutic potential for modulating cGAS-STING signaling to manage brain disorders." (PMID 42222892, 2026).
female reproductive diseases (1 paper, 2024). "Some studies have found that the cGAS-STING pathway is over-activated in certain female reproductive system diseases, leading to an increased inflammatory response that promotes the development of the disease." (PMID 39445027, 2024). "Although studies on the relationship between the cGAS-STING pathway and female reproductive system diseases are still relatively limited, the research in this field is deepening." (PMID 39445027, 2024). "In recent years, more and more studies have shown that the abnormal activation or inhibition of the cGAS-STING signaling pathway is closely related to the occurrence and development of a variety of female reproductive system diseases." (PMID 39445027, 2024).
peripheral neuropathy (1 paper, 2025). A disorder affecting the peripheral nervous system. "Intriguingly, peripheral neuropathy is a common phenotype of several DNA damaging agents, such as doxorubicin, which can damage mtDNA and lead to mtDNA-mediated cGAS-STING inflammation." (PMID 40175090, 2025).
CGAS also shares sentences with these, for which no sentence is quoted: viral diseases (8 papers); brain injury (5); pancreatic adenocarcinoma (4); alcoholic liver diseases (3); Anxiety (3); familial chilblain lupus (3); influenza (3); spinal cord injury (3); type 1 diabetes (3); acute monocytic leukemia (2); bone cancer (2); breast invasive carcinoma (2); cardiac ischemia (2); chronic hepatitis B (2); co-infection (2); diabetic retinopathy (2); endotoxemia (2); fatty liver (2); gastric adenocarcinoma (2); lung squamous cell carcinoma (2); Merkel cell carcinoma (2); Niemann-Pick disease type C (2); Polyarthritis (2); prediabetes (2); rectal adenocarcinoma (2); renal failure (2); renal medullary carcinoma (2); thyroid cancer (2); Ureteral obstruction (2); acute myocardial infarction (1).
A further 79 diseases each share a sentence with CGAS in 1 paper.